BRCA1 (BRCA1 DNA repair associated)
Diseases named in the same sentence as BRCA1 in open-access papers (continued):
Sharing a sentence is not in itself a finding about the gene and the disease.
cancer (continued). "The DUX4 target HSATII is expressed in a number of cancers, and it has been shown that mouse cells lacking the genome caretaker gene Brca1 aberrantly transcribe satellite sequences leading to genome instability." (PMID 24278031, 2013). "It is worthwhile to note that while mouse models of Brca1-dependent mammary tumorigenesis yield tumors with many of the characteristics of the human cancers, these models do not fully mimic the human situation." (PMID 23802008, 2013). "Moreover, the percentage of HIF-1α expression was significantly higher in the BRCA1-2 carriers (median value 15%, range 0–70) than in BRCAX cancers (median value 3%, range 0–64) (p<0.05), and in the sporadic group (median value 0%, range 0–60) (p = 0.0002)." (PMID 23326384, 2013). "Our data show that cucurbitacin B suppresses the ability of BRCA1 defective cells to grow and migrate which probably because of the decrease in survivin via PKB inhibition, suggesting that this agent has anti-metastatic potential against the cancer cells." (PMID 23393598, 2013). "The observation that the role of BRCA1 in promotion of SCE following replication fork collapse is more profound in cells depleted of ATR provides the possibility of sensitizing cancer cells without functional of BRCA1 to PARP inhibitors by ATR inhibitors." (PMID 23388117, 2013). "siRNA-mediated BRCA1 knockdown results in suppression of HR repair in several cancer and non-cancer cell model systems." (PMID 23388100, 2013). "Here, we studied promoter methylation status of key tumour suppressor genes involved in different cellular pathways and thought to be important in cancer development and progression, namely, p16 (cell cycle regulation), DAPK (apoptosis) BRCA1 (DNA repair) and GSTP1(protection of DNA)." (PMID 23596512, 2013). "VEGF, HIF-1α expression and MVD in BRCA1-2, BRCAX and Sporadic cancers." (PMID 23326384, 2013). "In summary, our findings show that RAD21 expression is associated with a poorer prognosis in BRCA2 and BRCAX, but not in BRCA1 cancers." (PMID 22537934, 2012). "BRCA1 cancers are more likely to show a basal phenotype, with 80% to 90% of BRCA1 cancers being negative for ER and HER2 and positive for basal cytokeratins." (PMID 22537934, 2012). "We tested the applicability of the evaluated tNGS method on E. coli, as a simple model to optimize the process, and human genomic samples in three experimental stages of increasing scope and complexity, culminating in a SNP concordance evaluation for the BRCA1 and BRCA2 cancer genes." (PMID 22913592, 2012). "This is despite our finding that RAD21 does not correlate with survival in BRCA1 cancers and the higher use of chemotherapy in BRCA1 cancers." (PMID 22537934, 2012). "In the third stage, we focused on enriching pools of barcoded libraries of HapMap individuals for non-repeat-masked regions of two clinically relevant human cancer genes (BRCA1 and BRCA2)." (PMID 22913592, 2012). "The distinctive profile of small deletions with rearrangement breakpoints showing overlapping microhomology in BRCA1 and BRCA2 mutant cancers is therefore compatible with these processes being defective and of NHEJ or other error-prone mechanisms of DSB repair acting in their place." (PMID 22608084, 2012). "Ectopic expression of BRCA1 in ovarian cells may induce the expression of FST and this FST expression in turn plays an antagonistic role to inhibit the cancer promoting function of activin." (PMID 22685544, 2012). "Considering that Cdk12 regulates the expression of several cancer-related genes, such as BRCA1, it comes as no surprise that the dysregulation of Cdk12 has been identified in several cancers." (PMID 22512864, 2012). "RAD21 expression correlated with shorter survival in BRCA2 (P = 0.006) and BRCAX (P = 0.008), but not BRCA1 cancers (P = 0.713)." (PMID 22537934, 2012). "Responses were filtered for eligibility based on BRCA1+ status, no prior cancer diagnosis, and no prior mastectomy." (PMID 26097796, 2012).
cancer (continued). "Case-report: lack of response of a chemonaive BRCA1-related cancer to the 1st line epirubicin-docetaxel combination, than major response to the 2nd line single-agent cisplatin." (PMID 21819606, 2011). "In this study, we further evaluated the effect of M344 on BRCA1 mRNA and protein expression, as well as its effect on cisplatin-induced cytotoxicity in various breast (MCF7, T-47D and HCC1937) and ovarian (A2780s, A2780cp and OVCAR-4) cancer cell lines." (PMID 21854619, 2011). "Paradoxically, under non-physiological over-expression conditions, BRCA1 induces apoptosis, and its silencing increases viability of certain cancer cells." (PMID 20051122, 2010). "None of the eight ER+ cancers that retained wt BRCA1 showed expression of basal cytokeratins CK5/6 or CK14." (PMID 21080930, 2010). "Further, it is apparent that the presence of wt BRCA1 is not required for ER expression in cancer tissues, in contrast to what has been suggested by some preclinical studies." (PMID 21080930, 2010). "There is currently great hope that these PARP inhibitors may represent a great opportunity to improve the therapy for BRCA1 and BRCA2 cancer patients." (PMID 21054854, 2010). "One potential limitation of the case-control study is that BRCA1 and 2 genetic testing information was not available for all of the women with sporadic cancers." (PMID 20149218, 2010). "All BRCA1 related carcinomas had a negative HER-2/neu receptor status when assessed, whereas in the control group 23.5% was positive (P = 0.005)." (PMID 20398395, 2010). "We expect that the majority of BRCA mutations diagnosed in the triple-negative, family history negative subgroup cancers will be BRCA1." (PMID 19298662, 2009). "Huge human losses caused by historical turbulences in the XX century, taken together with limited average life expectancy, led to the situation when many BRCA1 carriers simply failed to achieve the age of cancer manifestation due to premature death." (PMID 19338682, 2009). "We did not detect significant difference in cancer onset age in BRCA1/2 carriers harboring the different MDM2 SNP309." (PMID 19226467, 2009). "Unsupervised hierarchical clustering based on miRNA expression profiles showed no clear separation between the groups of carcinomas with different BRCA1/2 status." (PMID 19798417, 2009). "Excluding those cases with normal BRCA1 and BRCA2 protein expression in the primary, 20 (80%) recurrent carcinomas had increases in either BRCA1 or BRCA2 protein while five (20%) did not have an increase in expression of either protein." (PMID 19602291, 2009). "Indeed, a set of gene expression alterations due to the knockdown of endogenous BRCA1 has been identified in prostate (DU-145) and breast (MCF-7) cancer cells by DNA microarray analysis." (PMID 19002265, 2008). "Abnormalities in BRCA1 and BRCA2 in cancer have been reviewed elsewhere." (PMID 18047734, 2007). "Even among sporadic ovarian carcinomas, we showed that patients with advanced ovarian carcinoma negative for BRCA1 expression tended to show better survival than those with carcinoma positive for BRCA1." (PMID 19690636, 2007). "For the BRCA1 (BRCA2) group, the probability that CE MRI and mammography combined would be cost-effective would be 0.57 (0.82) and 0.71 (0.96) for a decision maker's willingness to pay per cancer detected of £20 000 and £30 000 respectively." (PMID 17016484, 2006). "If so, then agents that upregulate BRCA1 and BRCA2 in mammary epithelial cells may prevent cancer development." (PMID 16434996, 2006). "Even though BRCA1 cancers are thought to derive from basal cells that are ER negative, these cells are still under the influence of neighbouring ER-positive epithelial cells." (PMID 16538216, 2006).
cancer (continued). "Because the majority of BRCA1 tumors are ER-, these data question our assumption that tamoxifen does not prevent the outgrowth of ER- cancers." (PMID 16457695, 2005). "The present study includes men and women unaffected by cancer (i.e. no diagnosed cancer) attending nine centres that currently undertake the majority of BRCA1/2 testing in clinical cohorts in the UK." (PMID 15505627, 2004). "During genetic counselling prior to predictive genetic testing for BRCA1/2 it is important to ensure that decisions to proceed with genetic testing are informed and not motivated purely by cancer related worry." (PMID 11953874, 2002). "Furthermore, we evaluated the GIS also in 94 cancer samples from 16 entities without any detectable possible inactivating molecular alteration of BRCA1/2 or 20 other HRR genes as a control." (PMID 40278800, 2025). "Finally, HRD can be observed in 4.3% of BRCA1/2 and other HRR gene wildtype cancer samples, and may emerge as an independent biomarker for PARPi in the future." (PMID 40278800, 2025). "Biallelic loss of HRR genes, especially BRCA1, BRCA2, RAD51D, RAD51 C, and PPP2R2 A was linked to higher HRD scores in BRCA-associated cancers, while BARD1, RAD51D, RAD54L, BRCA1, and MRE11 were associated with elevated HRD scores in in other cancer types (non-BRCA cancers)." (PMID 40420266, 2025). "This study examines the relationship between BRCA1/2 carriers’ communication challenges and three factors: cancer status, comprehension of genetic information, and the genetic counseling pathway accessed (Traditional Genetic Counseling, TGC vs. Mainstream Cancer Genetics, MCG)." (PMID 40596937, 2025). "Given the described role of GSK3B-mediated phosphorylation of T334 in facilitating HR repair regardless of BRCA1 status, we asked whether interruption of T334 phosphorylation would sensitize cancer cells to the PARPi Olaparib." (PMID 41243969, 2025). "While most heterozygous carriers do not appear to have significantly increased cancer risks, susceptibility to cancer, including CRC, is well established for carriers of heterozygous pathogenic variants in FANCS/BRCA1, FANCD1/BRCA2, FANCN/PALB2, FANCJ/BRIP1, and FANCO/RAD51C." (PMID 41155398, 2025). "Moreover, loss/perturbation of EME1 phenocopies SETD1A loss in the absence of both BRCA1 and ATM and led to the restoration of HR, which was supported by data from cancer cell lines." (PMID 39994444, 2025). "Interestingly, PALB2 has a close interaction with BRCA1 and BRCA2, which could lead to malignant tumors." (PMID 40507905, 2025). "To further assess genetic interactions between BRCA1 and CASP3 and CASP7, we utilized Genetic inteRaction and EssenTiality neTwork mApper (GRETTA), a tool that leverages the publicly available data from the Cancer Dependency Map (DepMap, to perform a pan-cancer in silico genetic interaction screen." (PMID 39982959, 2025). "In a broader analysis across multiple cancers, high expression of TLK1 or TLK2 was significantly associated with poor prognosis in most of cancer types with wild-type BRCA1 (or low TLK1 associated with good outcome), but this was not seen in tumors with BRCA1 deficiency." (PMID 39844055, 2025). "Here, using next-generation sequencing we comprehensively surveyed genomes to identify DSBs in primary cells of non-malignant carriers of BRCA1 and BRCA2 mutations (BRCAmut), categorized as high-risk patients, to characterize the effects of homologous recombination (HR) loss on cancer initiation." (PMID 41350536, 2025). "However, some cancer‐related genes, such as breast cancer 1 early onset (BRCA1) and leukemia inhibitory factor (LIF), are not conserved." (PMID 41108536, 2025). "There were no other cancer-related germline mutations, including BAP1, BRCA1, or BRCA2." (PMID 40283643, 2025).
cancer (continued). "Additionally, DLC1 further inhibited the DYRK1A–EGFR axis, leading to DNA damage characterized by elevated levels of the double-strand break marker γH2AX and reduced regulation of DNA repair proteins p-BRCA1 and RAD51, ultimately resulting in the senescence of cancer cells." (PMID 40725041, 2025). "Other cancer germline mutations, such as BAP1, BRCA1, or BRCA2, were negative." (PMID 40283643, 2025). "In addition, vorinostat causes increased DNA double-strand breaks and functional homology-directed repair deficiency by down-regulating the expression of the DNA repair factors breast cancer 1 (BRCA1) and Rad51, resulting in increased cell death in IDH1 mutant cancer cells." (PMID 38988323, 2024). "However, patients with a positive family history of cancer showed a significantly higher mean BRCA1 gene expression of 37.29 ± 4.43 compared to those without (34.03 ± 3.28, P=0.001)." (PMID 39742378, 2024). "It is possible that the non-canonical properties of RAD51 are manifested when BRCA1 is absent, together with the genomic instability that is enhanced upon absence of WWOX, causes extensive DNA damage, supporting cancer development, and resistance to treatments." (PMID 38499540, 2024). "Furthermore, carriers of harmful BRCA1 and BRCA2 variants typically manifest the onset of cancer at earlier ages compared to non-carriers." (PMID 38809921, 2024). "Expression of innate immune system markers (APOBEC3A/B), DNA repair genes (BRCA1, BRCA2, PALB2, RAD51), cell cycle genes (CCNA2 and CCNE1), a cell proliferation gene (MELTF), and a T-cell regulator (Treg) marker (FOXP3) was elevated in cancer compared to precancer and controls." (PMID 39672307, 2024). "However, recent clinical evidence has shown that PARPi can prevent the growth of some cancers irrespective of their BRCA1/2 status, suggesting alternative mechanisms of action." (PMID 38767454, 2024). "The role of BRCA1 and BRCA2 proteins in the repair of DNA damage pathway raised the hypothesis that gBRCA carries have an increased sensitivity for chemotherapy, including both cancer as well as rapidly dividing cells such as bone marrow cells." (PMID 38345692, 2024). "This intricate interplay between UHRF1, BRCA1, and auxiliary factors underscores their significant contributions to DNA repair processes and gene regulation, positioning UHRF1 as a key player in the maintenance of genomic integrity and the prevention of diseases, particularly cancer." (PMID 39051184, 2024). "Indeed, cancer cells with a non-mutant BRCA1 gene were shown to suppress glycolysis by inhibiting the expression of the GLUT1 gene." (PMID 38745772, 2024). "In other non-CIMP-driven cancer types, including other subtypes of BC, it is not clear whether the observed tumour BRCA1 or RAD51C methylation arose from constitutional methylation or from an early cancer-acquired event." (PMID 39055334, 2024). "While BRCA1 and BRCA2 account for the majority of HRR mutations found in ovarian and breast cancer, deleterious mutations in other non-BRCA HRR genes are found in most cancer types and have been shown to confer sensitivity to PARP inhibitors." (PMID 38807759, 2024). "These suggest a possibility that cancer prevention by active pharmacological intervention may be possible for BRCA1 mutants to increase the quality of their life rather than preventive mastectomy and/or oophorectomy." (PMID 36639692, 2023).
cancer (continued). "Early signal targets involve the hallmark pathways of cancer survival (i.e., HER2, EGFR, mTOR, ALK, BRAF, RAS, CDK4/6, BRCA1, NTRK) with aggressive expansion of several hundred more now in active preclinical and clinical investigation or already registered as approved products." (PMID 38067319, 2023). "We had analyzed the overexpression and poor prognostic value of YWHAZ, BRCA1, and YWHAG in BRCA, so can we reasonably speculate on developing a drug to inhibit YWHAZ, BRCA1, and YWHAG-related functions to suppress cancer progression and make patients have a good prognosis." (PMID 36673982, 2023). "Thus, our results evidenced that both in early and late onset cancer patients, using the classical approach of BRCA1/2 testing, we would have lost a large number of cases resulted BRCA1/2 negative, but actually carriers of a PV/LPV in other genes." (PMID 37065479, 2023). "The absence of BRCA1 could potentially contribute to the persistence of cancer stem cells within breast tumors, thereby driving tumor progression and fostering resistance to treatment." (PMID 37762577, 2023). "Overall, 130 women with a newly found BRCA1/2 PV and no personal history of cancer were enrolled." (PMID 36767056, 2023). "Thus, as in C. elegans, human BRCA1 and BARD1 are not equivalent in function leading to different spectrum of cancers when mutated." (PMID 36716349, 2023). "Given the high throughput of BRCA1 and BRCA2 testing within the HCP, this clinical context was determined to be appropriate within which an initial tool could be developed, evaluated, and expanded upon for feasible clinical implementation at BC Cancer." (PMID 36660874, 2023). "Hence, modulating the degradation process of BRCA1, as well as other vital proteins in cell activity by TRIM21, may be feasible for cancer treatment and needs to be more profoundly investigated." (PMID 37864041, 2023). "The sample was highly educated, with almost half of the participants possessing a university degree, and, therefore, might not be entirely representative of the general population of cancer-unaffected BRCA1/2 PV carriers." (PMID 36767056, 2023). "In our study we did not have sufficient numbers of cancers with BRCA1, PALB2, or other rare HRR gene alterations to determine whether DARC Sign would assign BRCA2d status to such cancers." (PMID 36914848, 2023). "Therefore, the aim of this review is to fill this gap in the literature and explore the short- and long-term psychological consequences of receiving a positive genetic test result for BRCA1 or BRCA2 in women without a personal cancer history." (PMID 37185387, 2023). "Furthermore, it was shown that cancer cell lines lacking BRCA1/2 were sensitive to inhibitors of PARP1, whereas cells with functional BRCA1/2 were not." (PMID 37190285, 2023). "Interestingly one of the BRCA1 variants was found in one of the two cases with HER2 overexpression which is not usually a feature of BRCA1 cancers." (PMID 37592173, 2023). "The whole genomic sequencing and transcriptome analysis of cancer EVs and the recipient BRCA1-KO fibroblasts prior to and after exposure to cancer EVs confirmed that the active transfer of nucleic acids notably mutated cancer genes and their active transcription." (PMID 37371036, 2023). "BRCA1 carriers commonly develop aggressive cancers (triple-negative with high nuclear grade), with peak incidence in the 41–50 age-group, while BRCA2 carriers commonly develop cancers that are less aggressive (estrogen receptor (ER)-positive) with peak incidence in the 51–60 age-group." (PMID 37370730, 2023).